DAPK1 (death associated protein kinase 1)
Diseases named in the same sentence as DAPK1 in open-access papers (continued):
Sharing a sentence is not in itself a finding about the gene and the disease.
cancer (continued). "In contrast, DEGs with lower expression in patient relative to healthy control fibroblasts were enriched for one KEGG category ('Pathways in Cancer' as represented by the SMAD3, LAMA4, PML and DAPK1 genes), but no GO categories." (PMID 23036268, 2012).
neurological diseases (15 papers, 2013 to 2026). "In the context of excitotoxicity, particularly relevant in neurological disorders, death-associated protein kinase 1 (DAPK1) is recruited to extrasynaptic GluN2B-containing NMDARs." (PMID 41614918, 2026). "As a stress-responsive protein kinase, the dysregulation of DAPK1 expression or its activity has been implicated in a variety of neurological disorders." (PMID 38195518, 2024). "The results not only showed that DAPK1 plays a role in synaptic, cognitive and neuronal death-associated neuronal functions but also showed that DAPK1 is implicated in neurological diseases." (PMID 37047515, 2023). "A common serine/threonine (Ser/Thr) kinase known as death-associated protein kinase 1 (DAPK1) is essential for cell death in a number of neurological diseases." (PMID 36187290, 2022). "Considering the crucial role of microglial inflammasome/caspase-1/IL-1β axis in neuroinflammation, we propose that the inhibition of DAPK1 represents a potential therapeutic application for IL-1β-associated neurological diseases." (PMID 29967321, 2018). "Notably, DAPK1 has also been widely implicated in treatments for tumors and neurological disorders." (PMID 40611883, 2025). "Indeed, it has been reported that DAPK1 is substantially enriched in hippocampal synapses and has complex interactions with numerous synaptic proteins, which underlies the pathological influence of DAPK1 dysregulation on brain functions in neurological disorders such as AD." (PMID 38195518, 2024). "Our study provides insight into the pathological role of DAPK1 in the regulatory networks in the brain and new therapeutic strategies for the treatment of neurological diseases." (PMID 37047515, 2023). "In the present study, we report for the first time the function of DAPK1 in the brain and the role of DAPK1 in neurological diseases through transcriptional profiling of DAPK1-KO mice." (PMID 37047515, 2023). "Although DAPK1 is tightly regulated under physiological conditions, DAPK1 deregulation in the brain contributes to the development of neurological disorders." (PMID 31248062, 2019). "In summary, DAPK1 upregulation promotes neuronal damage, whereas downregulation of DAPK1 is beneficial for neuronal functions, which suggests that DAPK1 inhibition might exert therapeutic effects on many neurological diseases." (PMID 37047515, 2023). "In conclusion, our study revealed an effect of DAPK1 on neuronal functions and might provide insights into the development of novel therapeutic strategies for neurological diseases." (PMID 37047515, 2023). "DAPK1 has been shown to play a role in various neurological disorders." (PMID 35783103, 2022). "Thus, our study demonstrates that the DAPK1 may contribute to the pathogenesis of neurological diseases and could be a potential target for neurological diseases therapies." (PMID 37047515, 2023). "We and others previously found that the expression of DAPK1, another member of DAPK family, is increased in a plethora of neurological diseases, including AD, ischemic stroke, and TBI." (PMID 40032841, 2025). "However, although initial target validation evidence supports DAPK1 as a drug discovery target for neurological disorders, no clinically promising small-molecule DAPK1 inhibitors have yet been discovered." (PMID 27445685, 2016). "However, although initial target validation evidence with bioavailable kinase inhibitors supports DAPk1 as a drug discovery target for neurological disorders, no clinically promising small-molecule DAPk1 inhibitors have yet been discovered." (PMID 23880846, 2013).
neurodegenerative disease (13 papers, 2007 to 2025). A disorder of the central nervous system characterized by gradual and progressive loss of neural tissue and neurologic function. "Neuronal cell death that DAPK1 is implicated in is a critical process in the pathogenesis of various neurodegenerative diseases." (PMID 40918124, 2025). "Recently, death-associated protein kinase 1 (DAPK1) has been found to play essential roles in neuronal cell death and various neurodegenerative diseases, including AD." (PMID 32500074, 2020). "This understanding is crucial for developing therapeutic strategies targeting DAPK1 to mitigate its detrimental effects in neurodegenerative diseases." (PMID 40918124, 2025). "Further genetic analyses and animal studies have established that DAPK1 is indeed involved in the pathogenesis of a variety of neurodegenerative diseases." (PMID 38195518, 2024). "DAPK1 expression or activity is upregulated, and DAPK1 KO leads to a protective effect against neurodegenerative diseases." (PMID 35742817, 2022). "DAPK1 is the primary key protein kinase that regulates cell death in the brain in various neurodegenerative diseases such as PD and AD." (PMID 35783103, 2022). "Overall, the development of various inhibitors of DAPK1 activity in neurodegenerative diseases has contributed greatly to the discovery of therapeutic drugs for these diseases." (PMID 31248062, 2019). "DAPK1 seems to have a role in neuronal apoptosis, and has attracted interest as a drug discovery target for neurodegenerative disease." (PMID 18021406, 2007). "The development of drugs that specifically target DAPK1 signaling pathways could offer new avenues for the treatment of neurodegenerative diseases, providing hope for conditions that currently have limited therapeutic options." (PMID 40918124, 2025). "This review focuses on the role of DAPK1 in neuronal cell death and neurodegenerative diseases." (PMID 31248062, 2019). "Moreover, we focus on the major impact of DAPK1 deregulation on the progression of neurodegenerative diseases and the development of drugs targeting DAPK1 for the treatment of diseases." (PMID 31248062, 2019). "Therefore, this review summarizes the DAPK1 phosphorylation signaling pathways in various neurodegenerative diseases." (PMID 31248062, 2019). "Furthermore, DAPK1’s involvement in neurodegenerative diseases extends beyond AD." (PMID 40918124, 2025). "In particular, the upregulation of DAPK1 after TBI enhances the accumulation of cis P-tau, the main culprit of axonal injury in neurodegenerative diseases." (PMID 40032841, 2025). "DAPK1 regulates its downstream targets, such as tau, amyloid precursor protein, α-synuclein, and NR2B, as it serves mostly as a direct kinase in the development of neurodegenerative diseases, suggesting that DAPK1 might be a central regulator in these diseases." (PMID 35742817, 2022).
colorectal (2 papers, 2020 to 2023). "DAPK1 has a higher promoter hypermethylation frequency in colorectal carcinogenesis, which may be a genetic marker of colorectal carcinogenesis." (PMID 37576398, 2023).
hematologic malignancy (2 papers, 2015 to 2021). "These methylation changes in the promoter region of DAPK1 have been reported in a range of solid and hematological malignancies." (PMID 25435999, 2015).
infection (2 papers, 2014 to 2019). The state of being infected such as from the introduction of a foreign agent such as serum, vaccine, antigenic substance or organism. "Silencing of gp80, dapk-1, and bi-1 lead to a significant increase of infection levels in tick SG (p < 0.05) with a ratio of 2.29, 19.75, and 4.39, respectively." (PMID 31001128, 2019).
kidney disease (2 papers, 2019 to 2020). "Literature research indicated physiological relevance with regard to kidney disease for two proteins (AMBP, DAPK1)." (PMID 31083566, 2019).
central nervous system diseases (1 paper, 2025). "According to the literature, a close relationship exists between DAPK1 and central nervous system diseases." (PMID 39833100, 2025).
DAPK1 also shares sentences with these, for which no sentence is quoted: acute myeloid leukemia (9 papers); adenocarcinoma (5); head and neck squamous cell carcinoma (5); myelodysplastic syndrome (5); brain disorder (4); brain injury (4); endometrial carcinoma (4); bladder tumors (3); esophageal cancer (3); esophageal squamous cell carcinoma (3); laryngeal carcinoma (3); malignant mesothelioma (3); oral lichen planus (3); Seizure (3); Autoimmunity (2); breast adenocarcinoma (2); cervical tumors (2); endometrioid carcinoma (2); head and neck tumor (2); lung adenocarcinoma (2); Oral leukoplakia (2); pituitary tumor (2); thymoma (2); thyroid nodule (2); Type 2 Diabetes (2); urinary tract carcinoma (2); acute respiratory distress syndrome (1); adenoma (1); Apnea (1); autoimmune disease (1).
A further 79 diseases each share a sentence with DAPK1 in 1 paper.